Y_RNA (Y RNA )
Gene: Miscellaneous RNA gene on chromosome 10 (32,056,746 to 32,056,839, forward strand). Ensembl gene ENSG00000206660.
Homologues: Orthologues: chimpanzee Y_RNA (96% identical), macaque Y_RNA (90% identical). Paralogues in human: Y_RNA (84% identical), Y_RNA (83% identical), Y_RNA (82% identical), RNY3 (81% identical), Y_RNA (81% identical), RNY3P14 (80% identical), Y_RNA (80% identical), Y_RNA (79% identical), RNY3P1 (78% identical), RNY3P2 (78% identical), Y_RNA (78% identical), RNY3P5 (77% identical), and 89 more.